STAT3 (signal transducer and activator of transcription 3)
Diseases named in the same sentence as STAT3 in open-access papers (continued):
Sharing a sentence is not in itself a finding about the gene and the disease.
cancer (continued). "In summary, this approach allowed us to demonstrate the efficacy of these novel aptamers targeting STAT3 in cancer cells." (PMID 37298475, 2023). "The purpose of this study is to investigate the effects of genetic alterations of STAT3 and its expression on the development of cancer from the perspective of pan-cancer." (PMID 37724127, 2023). "In response to all these anti-neoplastic agents, cancer cells utilize STAT3 as one mechanism of escaping their therapeutic effects and promoting ADR." (PMID 36902166, 2023). "Experimental evidence supporting the participation of STAT3 in cancer progression will be further described." (PMID 37834225, 2023). "In view of their general consideration as positive regulators of cancer progression, STAT3 and p65 are regarded as therapeutic targets in cancer." (PMID 37190183, 2023). "Since STAT3 has been validated as an anticancer target, inhibition of STAT3 activity has been considered as a promising approach for cancer therapy." (PMID 36334221, 2023). "Pharmacologic inhibitors of STAT3 phosphorylation reduce several hallmarks of cancer, including GBM cell proliferation, survival, migration, invasion, and tumorigenicity." (PMID 37242454, 2023). "The improved understanding of the JAK/STAT3 signaling participation in cancer treatment has led to the increasing discovery of therapeutic intervention with JAK inhibitors." (PMID 37103357, 2023). "We found that STAT3 silencing dramatically overturned the cancer-promoting effect of the miR-26b-5p inhibitor on cells." (PMID 36737782, 2023). "For example, following vascular endothelial growth factor (VEGF) release by cancer cells, new blood vessels are formed via a STAT3 signaling axis." (PMID 37173951, 2023). "STAT3 is a crucial molecular hub in malignant tumors that plays important roles in promoting the production of immunosuppressive factors and inhibiting the expression of critical immune regulators." (PMID 38136311, 2023). "Napabucasin itself inhibits several signaling pathways, such as Wnt, PI3K/Akt, and STAT3, and stands the inhibition of cancer cell stemness as one consequence, another as inhibition of cancer cell proliferation." (PMID 37570646, 2023). "These aspects of STAT3 functionality emphasize the need to determine in much detail and precision the particularities of STAT3 control in different cancer settings." (PMID 37190183, 2023). "Our subsequent xenograft study underscored that PRMT6 overexpression led to a significant increase in lung metastasis nodes and weight while shortening the overall survival time of mice harboring STAT3 WT cancer cells." (PMID 37813837, 2023). "This deactivation of STAT-3 can suppress cancer-related inflammation and reduce the immune-suppressive environment of tumors, leading to the activation of antitumor immunity and the enhancement of cytototoxic T-cell effector functions." (PMID 37701157, 2023). "The IL6/JAK/STAT3 signaling pathway is frequently activated in various human cancers driving cell proliferation, migration/invasion, and cancer metastatic dissemination." (PMID 37173331, 2023). "STAT3 can also regulate metabolism-related genes that favor cancer progression and promote angiogenesis via the upregulation of VEGF." (PMID 37511453, 2023). "We observed that the expression level of p-STAT3 is positively correlated with the level of KDF1 in the cancers (r = 0.458, p < 0.01)." (PMID 38137415, 2023). "Several signaling pathways, e.g., the MAPK and JAK2/STAT3 pathways are involved in hsa-miR-135a-mediated cell proliferation and cancer progression." (PMID 37468555, 2023). "Among the STAT family members, STAT3 and STAT5 are well known for their roles in promoting cancer progression, especially STAT3, which is currently considered as a promising target for cancer therapy." (PMID 37095176, 2023).
cancer (continued). "STAT3 gene is often highly expressed in various cancers and can lead to therapy resistance by upregulating expression of anti-apoptotic proteins, stimulating DNA repair and cell proliferation." (PMID 36774402, 2023). "LncRNAs activated by TGF-β (lncRNA-ATB) promote EMT and metastasis by competitive binding of miR-200 and the survival of cancer cells by activating interleukin (IL)-11/signal transducer and activator of transcription 3 (STAT3) signal pathway." (PMID 36874003, 2023). "A number of other studies also demonstrate inhibition of the STAT3 signaling pathway in various types of cancer cells by niclosamide." (PMID 36675241, 2023). "Several signal pathways are involved in the regulation of cancer stem cell proliferation and differentiation, such as the STAT3, Wnt, and PI3K/Akt pathways." (PMID 37570646, 2023). "We additionally showed that C188-9, an experimental STAT3 inactivator currently in human clinical trials of cancer, rescued several molecular phenotypes relevant to AD in cell culture-based phenotypic assays." (PMID 36577843, 2023). "STAT3 also plays a critical role in regulating immune evasion, making it an attractive target for cancer therapy." (PMID 37047688, 2023). "The activation of STAT3 and TGF-β signaling is frequently detected in human cancers and is implicated in the proliferation and metastasis of various cancers." (PMID 38136312, 2023). "Interleukin 6 sends signals to the cell nucleus via a signal transducer to Transcription Activator 3 (STAT3), an oncoprotein activated in many cancerous tumors." (PMID 36981858, 2023). "Since STAT3 is expressed in almost all carcinomas, it is thought that the anti-cancer effect of EPBS in various carcinomas is possible, and its efficacy in various carcinomas will be revealed through future studies." (PMID 37762016, 2023). "The apoptotic effect of EGFR can also lead to biased signaling downstream by STAT1 and STAT3 activation in cancer cell lines." (PMID 37259433, 2023). "RES downregulates NF-κB and STAT3 in MM cells, which are key targets in cancer therapy, and potentiates the apoptosis induced by BTZ in MM cells." (PMID 37628771, 2023). "Our results showed that the level of STAT3 DNA methylation was increased in the vast majority of cancers." (PMID 36977736, 2023). "In this review, we investigate the specific roles of STAT1 and STAT3 in normal physiology and cancer biology, explore their interactions with each other, and offer insights into therapeutic strategies through modulating their transcriptional activity." (PMID 38022653, 2023). "STAT signalling is mainly regulated by interleukin-6 (IL-6) and its family members, although new pathways regulating STAT3 in cancer were recently identified." (PMID 37298475, 2023). "Given the constitutive activation and critical oncogenic roles of STAT3 in cancers, STAT3 has become an emerging therapeutic target." (PMID 38051779, 2023). "Previous studies have shed light on better understanding the further relationship between HIF-1, Signal Transducer and Activator of Transcription 3 (STAT3), and IL-37 in cancer disorders." (PMID 37446282, 2023). "Molecules targeting signaling pathways such as NF-ĸB and STAT3 are often studied in inflammatory-based diseases including cancer." (PMID 36986550, 2023). "STAT3 is known to be hyperactive in several cancers including CRC, and to control proliferation, metastasis and angiogenesis." (PMID 37020037, 2023). "Such anticancer activities of napabucasin mainly rely on the inhibition of cancer stemness by targeting signal transducer and activator of transcription 3 (STAT3) and its related gene inhibition." (PMID 37570646, 2023). "Among the STAT family proteins, STAT1 to STAT6, it was revealed that STAT3 functionally plays an important role in manipulating the biological activities of cancer cells, by affecting their energy metabolism, that is, the metabolism of glucose and lipids." (PMID 36899895, 2023).
cancer (continued). "Reflecting the necessity of STAT3 in cancer pathogenesis, inhibition of STAT3, by genetic or pharmacologic means, inhibits the survival and proliferation of malignant cells in many experimental systems." (PMID 38022653, 2023). "EGFR-mediated STAT3 signaling activation promotes the proliferation and glycolysis in various cancers." (PMID 37944197, 2023). "STAT3 is a central player in cancer because it controls the transcription of genes involved in the cell cycle, survival, metabolism (Warburg effect), epithelial–mesenchymal transition, chemoresistance, immunosuppression, angiogenesis, migration, and invasion." (PMID 37372319, 2023). "It should be noted that STAT3 activation affects both cancer stemness and immune evasion, which have emerged as important features of HCC initiation, development, and metastasis." (PMID 36721234, 2023). "Our results indicate that STAT3 can serve as a prognostic, sensitivity prediction biomarker and a target for immunotherapy, which has been of great value for pan-cancer treatment." (PMID 36977736, 2023). "Niclosamide is an FDA-approved antihelminthic drug that suppresses glycemia; this drug has also been reported to inhibit cancer malignancy through various mechanisms, including Wnt/β-catenin, mTORC1, STAT3, NFκB, S100A4 signaling, and other signaling pathways." (PMID 36765890, 2023). "The results showed that STAT3 mRNA expression differed between patients with cancer and controls in the Sangerbox database." (PMID 36977736, 2023). "Activation of STAT3 can promote cell survival, proliferation, and angiogenesis, thereby contributing to the development and progression of cancer." (PMID 37946196, 2023). "IL-6/JAK1/STAT3 signaling has been recognized as a key mechanism for cancer drug resistance and cancer stemness." (PMID 37440925, 2023). "CUR changed the expression of EGFR, microRNAs and autophagy in cancer stem cells and influences the expression of different genes in the cancer cells, such as NF‐kB, STAT‐3 and AP‐1, as well as protein kinases, including MAPK and enzymes such as COX and LOX." (PMID 37697969, 2023). "The activation of signal transducer and activator of transcription 3 (STAT3) plays a critical role in cancer cell proliferation, survival, metastasis, and self-renewal." (PMID 37121974, 2023). "Activation of STAT3 is related to several biochemical mechanisms influencing human diseases, both in inflammation and in cancer." (PMID 37998389, 2023). "STAT3 is a transcription factor known to be basically activated in several human cancer cells as well as hematological tumors." (PMID 37344563, 2023). "Conglomeration of all our observations has suggested that MDSC secreted IL-6/IL-10/IL-1β are the supreme players regulating the drug resistance of cancer cells via STAT1/STAT3/NF-κB pathway." (PMID 38304256, 2023). "The increased activity of PI3K/AKT and STAT3 signaling pathways has effects on the transcriptional machinery of proto-oncogenes involved in cancer progression and invasiveness." (PMID 38139209, 2023). "JAK2/STAT3 signaling pathway activation takes key parts in carcinogenesis and progression of different kinds of cancers." (PMID 37716993, 2023). "Sustained activation of IL-6/JAK/STAT3 signaling is an important factor in the development of cancer induced by inflammation." (PMID 36995541, 2023). "TRIM28 was first identified as a STAT-binding partner and frequent crosstalk between IL-6/STAT3 and NF-κB has been observed in cancer progression." (PMID 37443302, 2023). "STAT3 is one downstream effector pathway for IL-6, and it is highly active in >50% of BCs, suggesting a cancer-promoting effect." (PMID 37512149, 2023). "Mechanistically, IGF1R blockade stimulated a STAT3-dependent increase in autocrine IGF2 production by cancer cells, which recruited macrophages and fibroblasts, leading to the production of CXCL8 and proangiogenetic and prometastatic actions." (PMID 36672737, 2023).
cancer (continued). "Taken together, recent findings provide validating facts explaining the STAT3’s role in cancer and the abrogation of its constitutive active state provides a new targeted strategy in cancer therapy." (PMID 38170015, 2023). "Several signaling pathways, including TGF-β/SMAD, PI3-K/Akt, JAK/STAT3, and Hippo, play critical roles in the progression of various cancers." (PMID 37709768, 2023). "IL-11 and its receptor, interleukin-11 receptor α (IL-11Rα) activate STAT3 signaling, which correlates with poor patient prognosis in most human cancers." (PMID 37240247, 2023). "Mechanistic analysis suggested that Nos2 and nitric oxide (NO) produced by MDSCs fostered CSC phenotypes via activating Notch and STAT3 pathways in cancer cells." (PMID 37377935, 2023). "It remains to be addressed by further studies, using tissue-specific conditional deleters, how various cell types employ STAT2 and STAT3 signals to control discrete functions in normal (i.e., organoid) vs. cancer (i.e., tumoroid) epithelium." (PMID 38001683, 2023). "STAT3 N-terminal domain is a promising molecular target for cancer treatment and modulation of immune responses." (PMID 37182134, 2023). "As an oncogene, STAT3 inhibitors/degraders can kill cancer cells directly or inhibit gene expression involving all other cancer hallmarks." (PMID 39872303, 2023). "STAT3 is a recognized signaling molecule related to cancer cell growth, chemoresistance, invasion, and angiogenesis in many types of cancers." (PMID 36961655, 2023). "STAT3 activation has been shown to play a role in cancer cell proliferation, immune invasion, apoptosis, angiogenesis, and metastasis." (PMID 37375849, 2023). "Secreted IL-6 binding to membrane IL-6R induces STAT3 expression which is aberrantly active in BCA to promote cancer proliferation and anti-apoptosis." (PMID 37480115, 2023). "Considering the effect of shionone on important targets in multiple cancers, such as NF-κB and STAT3, studies are also suggested for other cancers in the near future." (PMID 38202771, 2023). "Compounds not only effectively interfered with STAT3 activity, but the degree of inhibition by different compounds correlated well with the binding score and toxicity in STAT3-dependent cancer cells." (PMID 37182134, 2023). "Different clinical trials have favored STAT3 gene transcription targeting as effective for cancer treatment." (PMID 37765047, 2023). "It has recently been reported that ITGA2 promotes the invasion of malignant tumors by activating the STAT3 signaling pathway and subsequently upregulating PD-L1 expression." (PMID 37377917, 2023). "One of the targets used in cancer immunotherapy is STAT3, which is involved in cell proliferation, survival, differentiation, and angiogenesis." (PMID 37241895, 2023). "The impact of JAK-STAT signaling on cancer cell survival, proliferation, invasion of tumors, coupled with the hyperactivation of STAT3 and STAT5; has positioned the JAK-STAT pathway as a potential pathway for cancer therapy." (PMID 38127921, 2023). "Another driver of oncogenesis and metastasis is Signal transducer and activator of transcription 3 (STAT3), which is constitutively activated in many cancers, and has been shown to be activated via pesticide exposure." (PMID 37511154, 2023). "IL-6 acts directly on cancer cells to induce the expression of STAT3 target genes, including Cyclin D1, BCL2-like protein 1 (BCL-xL), VEGF, MMPs, IL-10, and TGF-β, thereby contributing to the maintenance of CSC properties." (PMID 37853413, 2023). "It has been evidenced that the inhibition of the JAK2/STAT3 pathway potentiates apoptosis in cancer cells." (PMID 37009004, 2023).
cancer (continued). "Constitutive activation and high expression of STAT3 are observed in many cancers; it functions as an oncogene, promoting cancer cell proliferation, migration, and immune escape, and inhibiting apoptosis." (PMID 37173892, 2023). "In recent years, inhibition of phosphorylation and methylation of STAT3 has been studied as an anti-cancer strategy, indicating that phosphorylation and methylation of STAT3 are promising targets." (PMID 36977736, 2023). "The TNF-α, nuclear factor-kB (NF-κB), STAT3, AKT, and COX-2 are linked with different stages of cancer progression and reported to regulate cancer proliferation, apoptosis, invasion, metastasis, and angiogenesis." (PMID 38067358, 2023). "Taken together, these data highlight microenvironment remodeling to further activate STAT3 signaling in epithelial cells towards cancer progression." (PMID 37884500, 2023). "The JAK/STAT3 signaling pathway is aberrantly hyperactivated in many cancers, promoting cell proliferation, survival, invasiveness, and metastasis." (PMID 37103357, 2023). "Cytokines and growth factors secreted in cancer cells can lead to persistent activation of STAT3 and, consequently, to tumorigenesis." (PMID 36979673, 2023). "This includes STAT1 and STAT3, which encode two STAT family transcription factors, both of which are involved in the maintenance of healthy and cancer stem cells, while STAT3 additionally has been proposed as a target for treatment in PM." (PMID 36740402, 2023). "In detail, activated transcription factors, such as FOXO1, HIF1A, STAT3, and JUN, regulate the expression of TGFB1, TGFB3, IL1B, and TNF, promoting cancer hallmarks associated with these ligands." (PMID 37370765, 2023). "SD‐36 highly selectively induces rapid degradation of STAT3 at low nanomolar concentration in cancer cells." (PMID 37261210, 2023). "Double immunohistochemical (IHC) analysis of CD163 and pSTAT3 expression showed that STAT3 activation was induced in cancer cells located near TAMs." (PMID 36961655, 2023). "These authors also found that PTK6 promoted the development and metastasis of cancer by increasing STAT3 phosphorylation and ZEB1 expression." (PMID 37932734, 2023). "In cancer treatment, napabucasin is a therapy that targets signal transducer and activator of transcription 3 (STAT3) pathways." (PMID 38094891, 2023). "It regulates key processes in cancer such as cell proliferation, metastasis, and immune suppression, motivating the search to identify or develop inhibitors for STAT3." (PMID 37430747, 2023). "It has been reported that aberrantly activated STAT3 is present in nearly 70% of human cancer types, including colorectal, lung, breast, prostate, liver, pancreatic, multiple myeloma, and leukemia." (PMID 37240202, 2023). "At the same time, STAT3 inhibitors can suppress cancer development, invasive activity, and migratory behavior through inhibition of EMT." (PMID 37651362, 2023). "Aberrant activation of the STAT3 signaling pathway plays a critical role in tumorigenesis and cancer progression." (PMID 37569363, 2023). "While STAT3 and Akt signaling pathways play a key role in promoting cancer metastasis, there are few studies and applications on the effects of the active ingredients of EL on cancer metastasis." (PMID 37049904, 2023). "In turn, NF-κB and STAT3 pathway activation elevates the expression of cytokines, which aggravates cancer cachexia." (PMID 37190306, 2023). "We found that a number of signaling networks and their components such as PI3K/Akt/mTOR, MMP‐2 and 9, Wnt/‐catenin, PARP, MAPK, NF‐κB, Caspase‐3/8/9, Bax, Bcl2, Smad4, Notch1, STAT3, Nrf2, and ROS signaling can be regulated in cancer cells by phytochemicals." (PMID 37132286, 2023). "Using CyTOF, we found that GCSF led to elevated pSTAT3 in Neut/MDSCs in both cancer models, in keeping with the role of STAT3 in upregulating genes controlling Neut/MDSCs survival, expansion, and inhibitory functions." (PMID 36911097, 2023).